ACKR2 (atypical chemokine receptor 2)
Diseases named in the same sentence as ACKR2 in open-access papers (continued):
Sharing a sentence is not in itself a finding about the gene and the disease.
melanoma (8 papers, 2016 to 2025). A malignant, usually aggressive tumor composed of atypical, neoplastic melanocytes. "If confirmed, targeting ACKR2 could represent a beneficial therapeutic approach in BRAF/NRAS-mutated melanoma patients." (PMID 40248897, 2025). "Additionally, ACKR2 deficiency affects melanoma cell metastasis to the lung regions in a mouse model." (PMID 37056937, 2023). "To further investigate the role of ACKR2 in human melanoma, we analyzed its impact on patient survival using data from The Cancer Genome Atlas (TCGA)." (PMID 40248897, 2025). "Based on these results, we next investigated the effects of genetic targeting and pharmacological inhibition of ACKR2 on the efficacy of anti-PD-1 therapy in the B16-F10 melanoma model." (PMID 40248897, 2025). "The data presented in this manuscript focus on CCL5 and CXCL10 as key indicators for evaluating the impact of regulating the expression of ACKR2 in melanoma model." (PMID 40248897, 2025). "In BRAF- and NRAS-mutant melanoma patients, low ACKR2 expression or high CCL5/CXCL10 levels correlated with improved survival and higher CD8+ T cell markers." (PMID 40248897, 2025). "The data presented here emphasize the potential of combining ACKR2 inhibition with ICB as a promising therapeutic strategy for melanoma." (PMID 40248897, 2025). "In particular, melanoma patients harboring BRAF and NRAS mutations may benefit from therapies targeting ACKR2." (PMID 40248897, 2025). "In a melanoma mouse model, we demonstrated that Ackr2 inhibition increases the release of proinflammatory chemokines CCL5 and CXCL10 and enhances the infiltration of NK cells, activated CD8+ and CD4+ effector T cells while reducing regulatory T cells (Tregs) in the TME." (PMID 40248897, 2025). "On the contrary, ACKR2 has a pro-tumorigenic role limiting the recruitment and the activation of protective immune cells in intestinal tumors in ApcMin/+ mice and in breast and melanoma metastatic models." (PMID 32957704, 2020). "However, the relationship between ACKR2 expression and BRAF/NRAS mutations in melanoma remains unclear and warrants further investigation." (PMID 40248897, 2025). "ACKR2 is also consistently involved in tumor progression in the skin and gastrointestinal tract by regulating pro-tumoral leukocyte infiltration, and plays a pro-tumorigenic role in ApcMin/+ mice bearing intestinal tumors and in breast and melanoma metastatic models." (PMID 32957704, 2020). "ACKR2–/– mice have been demonstrated to have increased killing activity of NK cells through enhanced CCR2 expression and NK infiltration into the CCL2-expressing melanoma tumor microenvironment." (PMID 35677043, 2022). "To examine roles for Ackr2 in metastasis, we initially used the B16F10 melanoma cell line model." (PMID 30158126, 2018).
autoimmune disease (7 papers, 2015 to 2024). A disorder resulting from loss of function or tissue destruction of an organ or multiple organs, arising from humoral or cellular immune responses of the individual to their own tissue constituents. "A role for ACKR2 on lymphatic endothelium in autoimmune disease is implied from studies of the ACKR2-deficient mice during experimental autoimmune encephalomyelitis (EAE) where encephalitogenic responses, including DC migration and T cell priming, were impaired." (PMID 31105685, 2019). "ACKR2, previously known as D6, through inhibiting inflammation, mediates the resolution of inflammation in various conditions such as infections, autoimmune diseases, cancer, and neurodegenerative conditions." (PMID 36899817, 2023). "In some studies, ACKR2, through inhibiting inflammation, mediates the resolution of inflammation in various conditions such as infections, autoimmune diseases, and cancer." (PMID 35677043, 2022). "The role of ACKR2 in the inflammatory response has been investigated in several animal models, including chemical- and bacterial- induced inflammation, autoimmune disease and alloimmune disease, but with limited exploration in viral infection." (PMID 36518752, 2022). "The general emerging picture is that ACKR2 acts as a negative regulator of inflammation, but contrasting results were published on its role in the control of adaptive immune responses and in autoimmune disease development." (PMID 28123388, 2016). "Since all of these functions play a critical role in the pathogenesis of autoimmune diseases and resulting tissue damage, ACKR2 may have decisive effects on both systemic autoimmunity and autoimmune organ injury." (PMID 38799420, 2024). "In contrast, ACKR2, like in other autoimmune diseases, may facilitate priming of autoimmune T cells which mediate organ injury." (PMID 38799420, 2024). "Given ACKR2’s regulatory role in inflammation and T-cell priming, it is critical that studies are now being conducted to explore further the expression and regulation of ACKR2 in the draining lymph nodes and inflamed tissues of patients with autoimmune disease." (PMID 35677043, 2022). "Conflicting phenotypes published could possibly be explained by the fact that ACKR2 is also controlling IL-17 production, a critical cytokine for inflammatory and autoimmune diseases." (PMID 28123388, 2016). "However, potential roles of ACKR2 in reducing inflammation and tissue injury in autoimmune disorders like systemic lupus erythematosus (SLE) and lupus nephritis are unknown, as well as its effects on systemic autoimmunity." (PMID 38799420, 2024). "However, ACKR2 may also facilitate autoimmune disease such as experimental autoimmune encephalitis by allowing efficient priming of autoreactive T cells in lymphoid organs enhancing encephalitogenic responses." (PMID 38799420, 2024). "We therefore investigated potential functions of ACKR2 in B6lpr mice modelling SLE and lupus nephritis as a prototypic autoimmune disorder." (PMID 38799420, 2024). "However, as ACKR2 is found in subsets of leukocytes, lymphatic endothelial cells and epithelial cells in resting and inflamed human tissues, including those affected by autoimmune disease, it seems likely that these cell types are responsible for Ackr2 expression in inflamed tissues in mice." (PMID 25348934, 2015).
Kaposi's sarcoma (7 papers, 2017 to 2022). A malignant neoplasm characterized by a vascular proliferation which usually contains blunt endothelial cells. "Conversely, downregulation of ACKR2 driven by Kras activation is associated with tumor progression in human Kaposi’s sarcoma and in a mouse vascular tumor model." (PMID 29445158, 2018). "ACKR2 is known to restrain angiogenesis in Kaposi’s sarcoma via inhibition of pro-angiogenic macrophages." (PMID 36518752, 2022). "Indeed, inactivation of ACKR2 in gene-targeted animals causes tumor-promoting inflammation in the skin and the gastrointestinal tract and a similar observation was made in Kaposi’s sarcoma, where ACKR2 expression is downregulated by the oncogenic KRAS pathway." (PMID 32957704, 2020). "As a consequence, in patients with high aggressive Kaposi sarcomas D6/ACKR2 is down-regulated." (PMID 28740576, 2017). "ACKR2 prevents tumor growth also when it is expressed by Kaposi's sarcoma cells where it is down-regulated by the oncogenic pathway KRAS/BRAF/MEK/MAPK, while in anaplastic thyroid carcinomas ACKR2 expression is downregulated by miR-146a." (PMID 30894861, 2019). "In Kaposi sarcoma, it has been shown that activation of the K-Ras-B-Raf-ERK pathway results in downregulation of ACKR2 expression, unleashing CCR2-mediated recruitment and activation of M2-like phenotype of macrophages, which support angiogenesis and tumor growth via producing VEGFA." (PMID 35677043, 2022).
colitis (5 papers, 2016 to 2025). Inflammation of the colon. "In ACKR2-deficient mice with colitis-associated colon cancer, it has been shown that there is an increased infiltration of mast cells into the tumor microenvironment." (PMID 35677043, 2022). "The results of this study and its contradiction with the outcomes of ACKR2 involvement in colitis-associated colon cancer suggests that ACKR2 effects on different conditions might be varied due to the contribution of several other factors." (PMID 35677043, 2022). "In terms of ACKR2, it has been shown that the expression of this decoy receptor has upregulated during the induction and development of colitis with dextran sodium sulfate (DSS) in mice." (PMID 35677043, 2022). "ACKR2 expression in colitis mucosa prevents migration of IL-17A-secreting Tγδ cells to this microenvironment, leading to exacerbation of colitis in mice." (PMID 35677043, 2022). "As mentioned in the tumor section, the absence of ACKR2 in mice can lead to colitis-associated colon cancer." (PMID 35677043, 2022). "In an experiment, it has been shown that ACKR2–/– mice develop experimental colitis by increased production of inflammatory chemokines (CCL3, CCL5, CXCL1, CCL2, and CXCL2) and elevated leukocyte infiltration (T cells, macrophages, B cells, and DCs) in the inflamed mucosa of the colon." (PMID 35677043, 2022).
experimental autoimmune encephalomyelitis (5 papers, 2015 to 2022). An autoimmune demyelinating disease of the central nervous system that is produced experimentally in animals by the injection of homogenized brain or spinal cord in Freund's adjuvant. "The role of ACKR2 in autoimmunity remains relatively unexplored, although Ackr2 deficiency reportedly lessens the clinical symptoms of experimental autoimmune encephalomyelitis induced by immunization with encephalogenic peptide (MOG35–55)." (PMID 25348934, 2015). "Previous studies have reported unexpected findings in ACKR2-/- mice when tested in some disease models, including protection from experimental autoimmune encephalomyelitis and reduced renal inflammation in diabetic nephropathy." (PMID 29176798, 2017). "Furthermore, D6/ACKR2 KO mice were protected in a model of experimental autoimmune encephalomyelitis (EAE)." (PMID 28603493, 2017). "In previous work, despite reduced numbers of CD207+EPCAM+ migratory DCs detected in the DLNs of ACKR2-/- mice at day 3 post immunization with antigen, deficiency of ACKR2 did not impair T-cell priming and subsequent development of experimental autoimmune encephalomyelitis." (PMID 36518752, 2022).
lung carcinoma (4 papers, 2013 to 2025). "The present results revealed that ACKR2 plays a critical role in the progression of CXCL14-induced lung cancer." (PMID 37056937, 2023). "The results revealed that chemokine CXCL14 promotes EMT and migration through ACKR2 in lung cancer for the first time." (PMID 37056937, 2023). "The most important aspect of the data was that ACKR2 is an essential receptor for CXCL14-promoted lung cancer metastasis." (PMID 37056937, 2023). "As a specific receptor for CXCL14 in lung cancer, ACKR2 mediates CXCL14-induced signaling that leads to cell motility." (PMID 37056937, 2023). "Results of IHC staining and western blotting for levels of ACKR2 in lung cancer were similar to the analysis of TCGA database samples, showing higher levels of ACKR2 expression in lung cancer tissues and lung cancer cells." (PMID 37056937, 2023). "Additionally, CXCL14 facilitates EMT and subsequent cell migration in lung cancer by transactivating the ACKR2/PLC/PKC/c‐Src signalling pathway." (PMID 40162549, 2025). "The elimination of ACKR2 abolished the CXCL14-promoted phosphorylation of PLCβ3, PKCα, and c-Src and lung cancer cells." (PMID 37056937, 2023). "Moreover, transfection of ACKR2 siRNA prevented CXCL14-activated PLCβ3, PKCα, and c-Src phosphorylation, indicating that CXCL14 promoted lung cancer cell migration and EMT through activation of ACKR2/PLCβ3/PKCα/c-Src signaling pathway." (PMID 37056937, 2023). "Therefore, we investigated the role of ACKR2, CXCR4, and GPR85 in lung cancer." (PMID 37056937, 2023). "Additionally, ACKR2 was involved in CXCL14-triggered phospholipase Cβ3 (PLCβ3), protein kinase Cα (PKCα), and proto-oncogene c-Src signaling pathway and subsequently upregulated nuclear factor κB (NF-κB) transcription activity leading to EMT and migration of lung cancer cells." (PMID 37056937, 2023). "A meta‐analysis in all lung cancer tissues containing adenocarcinoma (LUAD) found that the expression of ACKR2 but not the other candidate receptors, CXCR4 and GPR85, was up-regulated in lung cancer studies." (PMID 37056937, 2023).
myocardial infarction (4 papers, 2013 to 2022). Gross necrosis of the myocardium, as a result of interruption of the blood supply to the area, as in coronary thrombosis. "In fact, CCR2 signaling promotes adverse remodeling in myocardial infarction, which was reversed upon ACKR2 upregulation, indicating that the scavenging of CC chemokines by ACKR2 regulates tissue homeostasis and favorable cardiac remodeling after MI and limits pathogenic inflammation." (PMID 35677043, 2022). "In myocardial infarction, ACKR2 was shown to prevent excessive infiltration of monocytes and neutrophils reducing adverse cardiac remodeling." (PMID 35625854, 2022). "ACKR2 deficiency resulted in elevated chemokine CCL2 and CCL3 levels in the ischemic heart of mice subjected to myocardial infarction." (PMID 35677043, 2022).
anaplastic thyroid carcinomas (3 papers, 2017 to 2025). "In particular, the majority of papillary thyroid carcinomas displayed a 3- to 5-fold decrease of D6/ACKR2 mRNA, while three out of four anaplastic thyroid carcinomas exhibited a 10- to 50-fold decrease of D6/ACKR2 expression." (PMID 28740576, 2017). "We identified D6/ACKR2 as a target of miR-146a repressive activity in anaplastic thyroid carcinoma cells and we found that the receptor was expressed in neoplastic thyroid specimens at much less extent than in normal thyroid tissue." (PMID 28740576, 2017). "On the basis of these observations, we studied in vivo the role of D6/ACKR2 restoration in anaplastic thyroid carcinoma cells." (PMID 28740576, 2017). "The low levels of D6/ACKR2 in primary human thyroid carcinomas and its ability to decrease leukocytes recruitment in vitro and in vivo following its over-expression in anaplastic thyroid carcinoma cells identify a protective role of D6/ACKR2 also in thyroid cancer." (PMID 28740576, 2017).
cervical cancer (3 papers, 2020 to 2025). A primary or metastatic malignant neoplasm involving the cervix. "Emerging evidence in cervical cancer models indicates that ACKR2 promotes CD8+ T cell senescence and tumour recurrence." (PMID 40318012, 2025).
adenoma (2 papers, 2020 to 2022). A neoplasm arising from the epithelium. "The downregulation of ACKR2 expression in adenomas insignificantly increased along with cumulated risk for malignancy, expressed as a sum of high-risk factors such as the presence of villous component, high-grade of dysplasia, and adenoma size exceeding 10 mm." (PMID 33374792, 2020). "In another study, ACKR2 expression was tracked to analyze the trend of expression through the conversion of an adenoma into an adenocarcinoma sequence." (PMID 35677043, 2022). "Collectively, during the adenoma procedure, ACKR2 expression was insignificantly increased, and then its expression declined insignificantly in the process of malignancy." (PMID 35677043, 2022). "Both in adenomas and adenocarcinomas, the observed ACKR2 downregulation resulted from changes in expression in neoplastic tissue while receptor expression in normal mucosa remained relatively stable at subsequent steps of adenoma-adenocarcinoma sequence." (PMID 33374792, 2020). "Gene expression analysis conducted here demonstrated that the degree of ACKR2 downregulation was similar in adenomas and adenocarcinomas." (PMID 33374792, 2020). "Expression rate (normal-to-adenoma) of ACKR2 was insignificantly higher in villous adenomas, which was a result of insignificantly lower receptor expression in polyp tissue of villous as compared to tubular and tubulovillous type." (PMID 33374792, 2020). "As compared to the 2.7-fold lower expression on average in neoplastic tissue, patients with score three adenomas had ACKR2 expression lower by 8.2-fold." (PMID 33374792, 2020). "Moreover, the highest downregulation of ACKR2 was at the point that adenoma cells are capable of being malignant." (PMID 35677043, 2022). "Moreover, the expression ratio of ACKR2 was decreased along with elevating tumor grade (adenoma to adenocarcinoma), whereas its expression was elevated through normal to pathological in adenoma tissues." (PMID 35677043, 2022). "The highest normal-to-pathological expression rates, and thus the most pronounced ACKR2 downregulation in neoplastic tissue, were demonstrated in polyps with the highest potential for malignancy, that is, in large adenomas with a high-grade of dysplasia and villous growth pattern." (PMID 33374792, 2020). "Likewise, we showed that ACKR2 expression in adenomas and sporadic CRC was downregulated in pathological tissue as compared to adjacent macroscopically normal mucosa." (PMID 33374792, 2020). "ACKR2 expression ratio (normal-to-pathological) increased insignificantly up-to score three and subsequently decreased significantly along with increasing malignancy, indicating maximal receptor downregulation in adenomas with the highest potential for malignancy." (PMID 33374792, 2020).
autoimmune disorders (2 papers, 2015 to 2024). "Conversely, ACKR2-facilitated migration of tissue-resident DCs carrying local antigens to draining lymph nodes to induce tolerance may again protect from autoimmunity and inflammation." (PMID 38799420, 2024). "However, we report here that Ackr2-deficient mice, on two separate genetic backgrounds, are not less susceptible to autoimmunity induced by immunization, and in some cases develop enhanced clinical symptoms." (PMID 25348934, 2015). "In the models we have examined, and using mice on two different genetic backgrounds, we find that deletion of Ackr2 does not suppress T-cell priming or provide protection against autoimmunity." (PMID 25348934, 2015).
colon adenocarcinoma (2 papers, 2022 to 2025). "Results showed that ACKR2 mRNA expression in colon adenocarcinoma tissues was decreased compared to unaffected mucosa." (PMID 35677043, 2022). "Since ACKR2 downregulation has been shown to contribute to the progression of colon adenocarcinoma, the correlation of ACKR2 expression in tumor tissues was analyzed to introduce its capability of being a biomarker in colon adenocarcinoma." (PMID 35677043, 2022). "Therefore, colon adenocarcinoma cells by downregulation of ACKR2 promote chronic inflammation and an immunosuppressive microenvironment to facilitate evasion of tumor cells from potent immune responses, suggesting ACKR2 as a potential biomarker for analyzing the development of colon adenocarcinoma." (PMID 35677043, 2022).